TDO2 (tryptophan 2,3-dioxygenase)
Diseases named in the same sentence as TDO2 in open-access papers (continued):
Sharing a sentence is not in itself a finding about the gene and the disease.
lung carcinoma (17 papers, 2016 to 2025). "RNAseq data for the 7 lung cancer cell lines (Minna lab, dbGaP Study Accession phs001823.v1.p1), we determined that TDO2 mRNA was elevated in A549, H1792, H2347, and H2228 cells, while IDO1 and IDO2 were low in most cell lines." (PMID 37985999, 2023). "On the other hand, some lung cancer cells also induce tryptophan 2, 3‐dioxygenase (TDO2; another rate‐limiting enzyme in Trp‐catabolism)‐positive myofibroblasts adjacent to the cancer region." (PMID 34379869, 2022). "Expression of tryptophan 2,3-dioxygenase (TDO2) by CAFs isolated from lung cancer also promotes tryptophan degradation in kynurenines (Kyn) that inhibits DCs differentiation and functions." (PMID 29545811, 2018). "In a lung cancer study, it was found that the impaired differentiation and function of DCs was due to tryptophan degradation, which was caused by both CAF-released IDO1 and lung-cancer-derived galectin-1-induced tryptophan 2,3-dioxygenase (TDO2)." (PMID 40805183, 2025). "Furthermore, tryptophan 2,3-dioxygenase (TDO2) secreted by CAFs inhibited the differentiation and function of DCs in a transplantable model of lung cancer, whereas TDO2 inhibition increased DC function and T cell responses." (PMID 37007004, 2023). "Moreover, we also demonstrate that lung cancer-derived galectin-1 contributes to the upregulation of TDO2 in CAF through an AKT-dependent pathway." (PMID 27050278, 2016). "Galectin-1 derived from lung cancer is one of the culprits of DC cell incapacitation, and it has been demonstrated that this phenomenon is mediated by the galectin-1-CAF axis and mainly associated with the tryptophan 2,3-dioxygenase (TDO2)/kynurenine axis in CAFs." (PMID 40244052, 2025). "Wu and colleagues recently reported that platinum-resistant non–small cell lung cancer tumors harnessed TRP catabolism via IDO1 and TDO2 to promote cell survival and immune evasion." (PMID 38451784, 2024). "In lung cancer, inhibition of DCs differentiation and function was shown to be mediated via CAF-secreted tryptophan 2,3-dioxygenase (TDO2)." (PMID 31428105, 2019). "Knockdown of galectin-1 loses the inductive effect of CL1-5 cancer cells on TDO2 expression and Kyn production in LCAF, suggesting that lung cancer-derived galectin-1 is responsible for TDO2 induction in LCAF." (PMID 27050278, 2016). "TDO2 is expressed in various cancers, and Perez‐Castro's analysis of tumor mRNA in TCGA revealed a downregulation of IDO1 along with an upregulation of TDO in lung cancer." (PMID 40103267, 2025). "We chose 7 lung cancer cell lines based on the variable levels of expression of IDO1 and TDO2." (PMID 37985999, 2023). "In a transplantable model of lung carcinoma, for instance, CAF-secreted tryptophan 2,3-dioxygenase (TDO2) was shown to inhibit DC differentiation and function, whereas inhibition of TDO2 improved DC function and T cell responses with decreased experimental metastasis." (PMID 34177901, 2021). "Furthermore, the tryptophan 2,3-dioxygenase (TDO2) and indoleamine-2,3-dioxygenase (IDO) released by α-SMA+ CAFs isolated from lung cancer enhance tryptophan degradation in kynurenines (Kyn) and consequently inhibits DCs differentiation and functions." (PMID 31462327, 2019). "Furthermore, upregulation of TDO2 was found in LCAF adjacent to the cancer region, when compared to the fibroblast on the far side of cancer, in specimens taken from patients with lung cancer." (PMID 27050278, 2016). "We assessed whether lung cancer cells alter the expression of the two dioxygenase, IDO1 and TDO2, in LCAF." (PMID 27050278, 2016). "Importantly, this first publication utilizing AT-0174, showed efficacy in preclinical models of non–small cell lung cancer, inhibiting chemoresistant tumor growth, compared with single inhibition of IDO1, supporting that TDO2 or dual inhibition is necessary for a robust antitumor response." (PMID 38451784, 2024).
depression (15 papers, 2009 to 2025). "It has also been shown that polymorphisms of the human TDO2 gene are associated with mental disorders such as depression, schizophrenia, ADHD, or substance abuse." (PMID 38732064, 2024). "There is a significant amount of research suggesting that elevated Ido1 and Ido2 is associated depression-like behavior and elevated Tdo2 expression is linked to Schizophrenia." (PMID 27142940, 2016). "In several genetic analyses, human TDO2 gene polymorphisms have been potentially associated with psychiatric diseases, such as Tourette syndrome, depression, and autism." (PMID 19323847, 2009). "Increased tryptophan metabolism towards the production of kynurenine via indoleamine/tryptophan-2,3-dioxygenases (DOs: Ido1, Ido2, and Tdo2) is strongly associated with the prevalence of major depressive disorder in patients and the induction of depression-like behaviors in animal models." (PMID 27142940, 2016). "We found higher expression of Tdo2 in the CMS group than the C group, which may have led to higher depression-like behaviors in the CMS group because of deficient serotonin levels through regulation by Tdo2." (PMID 25774879, 2015). "Inflammation increases tryptophan 2,3-dioxygenase (IDO), an enzyme that diverts tryptophan into kynurenine synthesis, reducing serotonin expression and causing depression-like symptoms." (PMID 40108902, 2025). "Moreover, another postmortem brain study has reported decreased expression not only of QUIN but also indoleamine 2,3-dioxygenase (IDO) 1/2, and tryptophan-2,3-dioxygenase (TDO) in the ventrolateral PFC of suicide victims with depression." (PMID 30814929, 2019). "Our results suggest that the Tdo2 may be involved in the mechanism of depression development." (PMID 32962062, 2020). "The effects on depression are via IDO and Tryptophan-2,3-dioxygenase (TDO), with an increase in Kynurenine (KYN) in the Tryptophan (TRP) metabolic pathway, resulting in a reduced amount of Serotonin." (PMID 29046648, 2017). "Other dioxygenases with activity similar to IDO1, such as TDO2 and possibly IDO2, could play a role in increasing kynurenine levels in response to central LPS treatment to precipitate certain depression-like behaviors." (PMID 23866724, 2013). "Regarding depressive disorders, it could be proposed that processes such as inflammation or stress may induce increased tryptophan metabolism to kynurenine via indoleamine 2,3-dioxygenase (IDO) or tryptophan-2,3-dioxygenase (TDO), and therefore reduced tryptophan availability." (PMID 37847374, 2024).
melanoma (14 papers, 2019 to 2025). A malignant, usually aggressive tumor composed of atypical, neoplastic melanocytes. "Melanoma cells and surrounding liver tissue show positive TDO2 mRNA expression." (PMID 32050636, 2020). "Strikingly, IDO1, along with other kynurenine pathway genes previously targeted in melanoma (IDO2 and TDO2), also correlated with better outcomes in SKCM.met." (PMID 40427178, 2025). "In melanoma, increased expression of IDO1 or tryptophan 2,3-dioxygenase (TDO), another enzyme involved in metabolizing tryptophan to AhR ligands, increases the abundance of TAMs and polarizes to a more M2-like immunosuppressive phenotype." (PMID 38339226, 2024). "In syngeneic mice model of melanoma, depletion of Kyn in both plasma and tumor by Kyn-degrading enzymes kynureninase reduced Kyn levels in IDO1, TDO2 and IDO1/TDO2-expressing cancer cells and augmented effector T cells in tumor, without impact on Trp levels." (PMID 35173722, 2022). "Analysis of IDO1/TDO2 expression in the Cancer Genome Atlas (TCGA) database revealed that both IDO1 and TDO2 were upregulated in TNBC and melanoma relative to normal breast and skin tissues." (PMID 35780226, 2022). "This might suggest that even the high mutation burden subset of melanoma, which shows over-expression of both IDO-1 and IDO-2 but not TDO-2, does not respond to IDO-1 inhibitors and over-expression of all three genes are necessary for response to IDO-1 inhibitors." (PMID 34367262, 2021).
hepatocellular carcinoma (13 papers, 2019 to 2025). A malignant tumor that arises from hepatocytes. "At the same time, the overexpression of TDO2 is closely related to the occurrence and development of various cancers, especially showing significant prognostic value in malignant tumors such as hepatocellular carcinoma and lung adenocarcinoma." (PMID 40894479, 2025). "By RNA immunoprecipitation (RIP) using TDO2-specific antibodies and sequencing of the precipitated RNAs, the authors identified 645 known miRNAs and 138 novel miRNAs that can bind to TDO2 in human hepatocellular carcinoma (HCCLM3) cells." (PMID 38473229, 2024). "Recent studies have demonstrated that TDO2 is expressed in diverse tumor types, including hepatocellular carcinoma, non-small cell lung cancer, ovarian carcinoma, and renal cell carcinoma." (PMID 35733134, 2022). "Several studies have reported functional TDO2 expression in various human cancers including bladder, melanoma, and hepatocellular carcinoma." (PMID 34943977, 2021). "A hepatic‐Tdo2‐specific KO mouse is being constructed and the long‐term effects of TDO2 inhibition on liver function and overall metabolism (such as hepatic fibrosis, cirrhosis and even hepatocellular carcinoma) would be systematically studied in the near future." (PMID 39364706, 2024). "The ISX expression strike enhanced the levels of tryptophan catabolic enzymes, indoleamine 2,3-dioxygenase 1 (IDO1), tryptophan 2,3-dioxygenase, and immune checkpoints regulators PD-L1 and B2-7 (CD86) in hepatocellular carcinoma cells." (PMID 41417109, 2025). "In hepatocellular carcinoma (HCC) tissues, 3-HAA levels are significantly downregulated, while expression of 5-HT1D, KMO, and TDO2 is markedly upregulated." (PMID 38462620, 2024). "Together, these results indicate that TDO2 promotes the EMT of hepatocellular carcinoma through activating Kyn-AhR pathway, thereby participating in the metastasis and invasion of HCC." (PMID 33542896, 2020). "Although this study supports that the interaction between TDO2 and miR-126-5p plays a role in hepatocellular carcinoma, it is not clear whether the observed effects take place in specific cellular compartments due to limitations in the experimental systems that were used." (PMID 38473229, 2024).
colorectal cancer (9 papers, 2016 to 2025). A primary or metastatic malignant neoplasm that affects the colon or rectum. "It is believed that TDO2 plays a crucial role as a downstream effector in APC-deficient colorectal cancer." (PMID 40136551, 2025). "Overexpression of TDO2 is not only associated with poor prognosis in colorectal cancer, but also related to the clinical stage of colorectal cancer." (PMID 40136551, 2025). "They propose that TDO2 is implicated in amino acid metabolism, and its high expression suggests heightened activity in this pathway, which may unfavorably impact the prognosis of colorectal cancer patients." (PMID 40136551, 2025). "Based on the clinical data, TDO2 is overexpressed in the tumor tissue of colorectal cancer patients." (PMID 40136551, 2025). "Reports revealed that inhibition of TDO2 can repress the proliferation, migration and invasion of ovarian cancer and colorectal cancer." (PMID 36185201, 2022). "The previous study has proven that TDO2 expression was highly elevated in colorectal cancer, and knockdown of TDO2 significantly inhibited the proliferation, migration, and invasion of colorectal cancer cells." (PMID 36118672, 2022). "Further investigation found that the TDO2-AHR pathway directly regulates the expression of Wnt signal target gene LGR5 to maintain colorectal cancer stemness and regulate the development of colorectal cancer." (PMID 40136551, 2025). "Although the antitumor efficacy of immune checkpoint blockade (ICB) has been proved in colorectal cancer (CRC), the results are unsatisfactory, presumably owing to the presence of tryptophan metabolism enzymes indoleamine 2,3-dioxygenase 1 (IDO1) and tryptophan 2,3-dioxygenase 2 (TDO2)." (PMID 35571116, 2022).
triple-negative breast carcinoma (9 papers, 2018 to 2024). An invasive breast carcinoma which is negative for expression of estrogen receptor (ER), progesterone receptor (PR), and human epidermal growth factor receptor 2 (HER2). "Studies in triple-negative breast cancer cells have also indicated that knockdown of TDO2 induces apoptosis in these cells in vitro, suggesting a cancer cell intrinsic dependency on the Trp catabolizing enzymes for survival." (PMID 37985999, 2023). "Similar induction was also observed in triple-negative breast cancer cells, but intriguingly, only TDO2, was basally higher in cells cultured under low attachment conditions than in monolayer cultures, indicating a cell-type or cancer-type specificity." (PMID 37985999, 2023). "NC D’Amator provided evidence that the TDO2-AhR signaling axis might facilitate anoikis resistance and metastasis in triple-negative breast cancer." (PMID 35831824, 2022). "Notably, in triple negative breast cancer, the TDO2-AhR signaling axis promotes metastasis and resistance to anoikis." (PMID 35203450, 2022). "Furthermore, in an in-vitro model of triple-negative breast cancer, TDO2 inhibition by 680C91 significantly reduced intracellular KYN levels, leading to their increased sensitivity to the process of programmed cell death, as well as reduced their ability to proliferate, migrate and invade." (PMID 34201791, 2021). "Anchorage-independent triple-negative breast cancer (TNBC) cells exhibit elevated levels of the tryptophan (TRP)-catabolizing enzyme tryptophan 2,3-dioxygenase 2 (TDO2) compared with the same cells grown under two-dimensional culture conditions." (PMID 39311710, 2024).
ovarian carcinoma (7 papers, 2019 to 2025). A malignant neoplasm originating from the surface ovarian epithelium. "In the current study, we compared proliferation following the genetic knockdown of IDO1, TDO2, and AhR in ovarian cancer cell lines and observed a more robust antiproliferation response in the setting of TDO2 knockdown." (PMID 38451784, 2024). "Meanwhile, tryptophan 2,3-dioxygenase (TDO2), the rate-limiting enzyme of the kynurenine pathway, was found to be upregulated in ovarian cancer tissues, which promotes tumor cell proliferation, migration and invasion." (PMID 36311734, 2022). "In addition, TDO2 is upregulated in ovarian cancer tissues and promotes the proliferation and migration of ovarian cancer cells." (PMID 41282989, 2025). "Although TDO2 mRNA and proteins are higher than those of IDO1 in TNBC, both enzymes can be expressed, and we find this to be the case in ovarian cancer as well." (PMID 39311710, 2024). "To investigate the relative contributions of IDO1 versus TDO2, we generated shRNA-mediated knockdown IDO1 and TDO2, as well as the downstream KYN receptor AhR in human ovarian cancer OVCAR3 cells." (PMID 38451784, 2024). "In this study, using preclinical models and clinical specimens, we determine that targeting TRP metabolism via a dual TDO2/IDO1 inhibitor reduces protumor intrinsic cell phenotypes as well as immunosuppressive markers in macrophages, which could be clinically impactful in ovarian cancer." (PMID 38451784, 2024). "Our analysis of the DepMap database revealed that low micromolar concentrations of epacadostat increased the growth of most ovarian cancer cell lines, providing additional confirmation that IDO1 inhibition alone is insufficient to reduce tumor cell growth without corresponding targeting of TDO2." (PMID 38451784, 2024).
colon carcinoma (6 papers, 2019 to 2025). "To determine the importance of Kyn to the growth of colon cancer cells, we compared the growth of normal HCECs and colon cancer cell lines in the presence of pharmacological inhibitors of TDO2 (680C91) and IDO (epacadostat)." (PMID 31416966, 2019). "However, in a recent study, it has been found that TDO enzyme was elevated in 40% of the samples from colon cancer patients, while TDO2 mRNA was reduced in few colon cancer cells lines." (PMID 32776284, 2020). "Key enzymes of tryptophan metabolism, such as indoleamine-2,3-dioxygenase 1, tryptophan-2,3-dioxygenase, and kynurenine monooxygenase, play essential roles in pathophysiological processes and have been found to be overexpressed in melanoma, ovarian cancer, breast cancer, and colon cancer." (PMID 37954130, 2023). "In colon cancer, kynurenine produced by IDO1 and TDO2 enzymes was shown to hinder immune surveillance and promote cancer stemness and liver metastasis via the TDO2-kynurenine-AHR pathway." (PMID 40647402, 2025). "We performed IHC for TDO2, TPH1, AHR, serotonin, and TPH2 in paraffin-embedded patient-derived normal and colon cancer tissues to confirm our TCGA results." (PMID 31416966, 2019). "Our results confirmed that SLC7A5, SLC1A5, TDO2, IDO1, and AHR were all elevated in colon cancer, while TPH1 was reduced." (PMID 31416966, 2019). "To validate these results, we performed RT-qPCR for SLC1A5, SLC7A5, TPH1, TDO2, IDO1, AHR, and MYC in colon cancer and normal tissue of the same patients." (PMID 31416966, 2019). "Elevated levels of the enzymes TDO2, IDO1, and AFMID combined with the Trp transporters SLC1A5 and SLC7A5 in colon cancer patients may lead to increased Trp and Kyn levels in colon cancer cells." (PMID 31416966, 2019). "We found that the enzymes IDO1 and TDO2 were elevated in ∼40% of the samples from colon cancer patients, and the enzyme AFMID, which is involved in the last step of the conversion of Trp into Kyn, was up-regulated in 80% of these samples of colon cancers." (PMID 31416966, 2019).
liver cancer (6 papers, 2021 to 2025). An epithelial or non-epithelial malignant neoplasm that arises from the liver. "Further investigations revealed that TDO2 facilitates the migration and invasion of liver cancer cells through the signal transduction pathway involving Wnt5a, a key ligand in the non-canonical Wnt signaling pathway." (PMID 40136551, 2025). "In this study, we attempted to investigate the biological role of miRNA-126-5p in the progression of liver cancer and its interaction with TDO2 to provide reference for the diagnosis and treatment of liver cancer." (PMID 35056756, 2022). "In humans, TDO2 is highly expressed in liver cancer and is involved in immune tolerance of liver cancer cells." (PMID 35056756, 2022). "Notably, a bioinformatics analysis of liver cancer-related data from the public gene expression database (GEO) has indicated that TDO2 expression is decreased in liver cancer tissues." (PMID 40136551, 2025). "IDO1 was elevated in 50% of liver cancer samples while IDO2, TDO2, and AFMID were predominantly downregulated." (PMID 38769298, 2024). "To further confirm the pro-tumor effects induced by TDO2, we established TDO2 overexpression SMC-7721 and HepG2 liver cancer cell lines, and cell proliferation or colony formation were evaluated." (PMID 34657635, 2021). "To further confirm the pro-tumor effects induced by TDO2, we established TDO2 overexpression SMC-7721 and HepG2 liver cancer cell lines, and western blotting, cell proliferation, and colony formation were evaluated." (PMID 34657635, 2021).
Anxiety (4 papers, 2016 to 2025). Intense feelings of nervousness, tension, or panic often arise in response to interpersonal stresses. "A repercussion of aberrant Tdo2 expression may be altered behavior such as those associated with schizophrenia and anxiety." (PMID 27799931, 2016). "Through annotation analysis of differential metabolite pathways, the result showed a significant elevation in the level of tryptophan 2,3-dioxygenase, indicating its involvement in anxiety regulation in P. trituberculatus." (PMID 39452949, 2024). "The deletion of TDO2 in mice resulted in lower anxiety-like behaviors than the wild type." (PMID 35744601, 2022).
bladder cancer (4 papers, 2019 to 2023). "Bladder cancer cells may upregulate enzymes like tryptophan 2,3-dioxygenase (TDO) or indoleamine 2,3-dioxygenase (IDO), leading to heightened tryptophan degradation." (PMID 37328580, 2023).